CD36 (CD36 molecule (CD36 blood group))
Diseases named in the same sentence as CD36 in open-access papers (continued):
Sharing a sentence is not in itself a finding about the gene and the disease.
breast carcinoma (continued). "Altogether, these results indicate that STAT3 and ERK1/2 inhibition decrease CD36 expression in co-cultured breast cancer cells." (PMID 34561446, 2021). "Previous work showed that after exogenous addition of oleic acid to breast cancer samples, CD36 expression increased, followed by accumulation of cytoplasmic lipid droplets only in CD36-expressing cells." (PMID 34071445, 2021). "Consistent with the context-specific CD36 expression, co-culturing breast cancer cells of distinct molecular phenotypes, with differentiated hADS, increased CD36 expression." (PMID 34561446, 2021). "Pascual and colleagues further demonstrated that short hairpin RNA-mediated depletion of CD36 significantly reduced metastases in models of melanoma (501mel) and breast cancer (MCF-7) in vivo." (PMID 34215227, 2021). "In breast cancer cells, CD36 expression increases with adipocyte conditioned medium and its activity is involved in adipocyte-induced migration and invasion." (PMID 34359819, 2021). "To this, we report an increased CD36 expression in breast cancer tissues invading surrounding adipose tissues and its tumour promoting function in adipocyte-breast cancer cell interaction." (PMID 34561446, 2021). "This supports recent studies wherein CD36 proved important for the migration and invasion of breast cancer cells and cervical cancer cells in vitro." (PMID 34215227, 2021). "To examine the molecular function of CD36 in adipocyte-breast cancer cell interaction, we established stable CD36 expression MCF-7 and MDA-MB-468 cell lines (CD36 expression cells)." (PMID 34561446, 2021). "In this study, we extended our previous studies to show that the CM of CD36+ FBs induced growth suppression, via apoptosis, in a subset of breast cancer cell lines." (PMID 34572749, 2021). "The expression levels of CD36 were higher in macrophages exposed to breast cancer cell debris compared to those co-cultured with viable breast cancer cells." (PMID 33809707, 2021). "In breast cancer patients, increased CD36 expression occurs, with increased expression of lipid transport receptors (LDL) and FABP4." (PMID 34561446, 2021). "This study aimed to explore the context-dependent role of CD36 in adipocyte-breast cancer interaction." (PMID 34561446, 2021). "In conclusion, our findings suggest that these ligands, secreted by CD36+ FBs, can be targeted for breast cancer treatment." (PMID 34572749, 2021). "Studies have highlighted the pro-tumorigenic and pro-metastatic actions of CD36 in various cancer types, including oral squamous cell carcinoma, breast cancer, and melanoma." (PMID 33232276, 2020). "Consistent with reports that CD36 is upregulated in breast cancer and glioblastoma, we found that CD36 is highly expressed in CRC as compared to normal mucosa." (PMID 32850342, 2020). "Fatty acid uptake mediated by CD36 has been found essential to initiate metastasis of human melanoma and breast cancer." (PMID 32733643, 2020). "For example, CD36 increased proliferation and migration of breast cancer cells and antagonised tamoxifen effects." (PMID 31895944, 2020). "It has been reported that siRNA-mediated inhibition of CD36 decreases cellular proliferation in MCF-7 breast cancer cells." (PMID 32850342, 2020). "CD36 neutralizing antibodies also inhibited growth of breast cancer cells, metastasis in mouse models of human oral cancer, and cancer severity in patient-derived prostate cancer xenografts." (PMID 33083663, 2020). "CD36 expression is increased when breast cancer cells are cultured with BMAs, and exogenous lipids are transferred to breast cancer cells by CD36 to promote the growth of cancer cells." (PMID 32674405, 2020). "Deletion of the CD36 gene in a mouse model of breast cancer significantly attenuated mammary tumor development." (PMID 32046099, 2020).
breast carcinoma (continued). "The presence of CD36+ metastasis-initiating cells correlated with a poor prognosis for numerous carcinomas, including breast carcinoma, and the inhibition of CD36 impaired the metastasis of breast tumor cells." (PMID 31766495, 2019). "For example, CD36 expression level in breast cancer stroma is considerably lower than that in adjacent tissues." (PMID 31410189, 2019). "Inflammatory factors (CCL5, IL-6, etc.)and transporters (MCT1, CD36, etc.)are potential targets for breast cancer treatment." (PMID 31500658, 2019). "The presence of CD36 on cancer cells initiates metastasis and correlates with an unfavorable prognosis for melanoma and breast cancer, and inhibition of CD36 impairs metastasis." (PMID 31655604, 2019). "In breast cancer, the growth and aggressiveness-initiating or -inhibiting functions of CD36 have been solidly reported, and the paradoxical regulations were also seen in pancreatic adenocarcinoma." (PMID 31484922, 2019). "Recent studies indicate that high CD36 expression is detected in breast cancer and CD36 function is important for cell growth in breast cancer cells and metastasis in metastasis-initiating breast cancer cells." (PMID 30388870, 2018). "Palmitic acid (a common saturated fatty acid, C16:0) or a high-fat diet enhances the metastatic potential of CD36+ metastasis-initiating breast cancer cells." (PMID 30388870, 2018). "More importantly, we identified that CD36 expression played a critical role determining the sensitivity of tamoxifen on growth of breast cancer cells." (PMID 30573731, 2018). "Tamoxifen inhibits estrogen receptor (ER)-positive breast cancer growth while CD36 potentiates cancer metastasis." (PMID 30573731, 2018). "In this study, we correlated the mortality of breast cancer patients to tumor CD36 expression levels." (PMID 30573731, 2018). "FABP4 and CD36 were scarcely expressed in breast cancer cell lines in the current study, so we focused on FABP5." (PMID 29914512, 2018). "In the present study, we determined if CD36 expression can function on proliferation and migration of breast cancer cells, particularly the ER-positive cells, thereby influencing the effect of tamoxifen on growth of breast cancer cells." (PMID 30573731, 2018). "This was in accordance with Guaita-Esteruelas’s study in which FABP4 and CD36 were found to be rarely expressed in the breast cancer cell lines MCF-7 and MDA-MB231 when detected by western blot." (PMID 29914512, 2018). "We also characterized the effect of CD36 on expression of genes for proliferation, migration and apoptosis in breast cancer cells." (PMID 30573731, 2018). "Nobiletin inhibited CD36-dependent breast cancer cell migration and invasion as well as CD36-mediated tumor sphere formation." (PMID 29914089, 2018). "First, the mRNA expression levels of FABP4,FABP5 and another putative FA translocase, CD36, were detected in various breast cancer cell lines." (PMID 29914512, 2018). "Activation of breast cancer cell growth by oleic acid is correlated to its cellular uptake through CD36 action." (PMID 30573731, 2018). "Our study also suggests an inverse correlation between CD36 expression and sensitivity of tamoxifen on growth of breast cancer cells." (PMID 30573731, 2018). "Next, we determined the effect of CD36 expression on breast cancer cell migration by conducting Transwell and wound healing assays." (PMID 30573731, 2018). "In this study, we determined that regulation of ERK1/2 activity is important for CD36-mediated growth of breast cancer cells." (PMID 30573731, 2018). "Clinically, the presence of CD36+ metastasis-initiating cells correlates with a poor prognosis for numerous types of carcinomas, and inhibition of CD36 also impairs metastasis, at least in human melanoma- and breast cancer-derived tumors." (PMID 29188139, 2017). "N-terminal recombinant fragment of THBS2 inhibited breast cancer growth and metastasis by CD36 mediated activation of endothelial cell apoptosis." (PMID 29190912, 2017).
breast carcinoma (continued). "Conversely, lipoprotein lipase (LPL) and CD36 are frequently highly expressed in breast cancer tissue, and their overexpression in breast cancer cell lines activates a lipolytic pathway that enhances growth in culture." (PMID 27635066, 2016). "Altogether, these data provide evidence for an essential role of the CD36 protein in the ferroptotic process induced by the saturated fatty acid PA, opening potential new therapeutic approaches promoting ferroptosis in the most aggressive breast cancers." (PMID 41672971, 2026). "This suggests that the dual inhibition of exogenous FA uptake and endogenous SCD-1-mediated de novo lipogenesis using CD36 and PI3K inhibitors might be a viable therapeutic approach in anti-HER2 resistant breast cancer with PTEN-loss." (PMID 39920872, 2025). "Along this line, silencing CD36 decreases viability and migration with more potent effects on ER-positive than ER-negative cells, and further restored tamoxifen-mediated inhibition of cell growth in tamoxifen-resistant breast cancer." (PMID 39920872, 2025). "The combination therapy with CD36 inhibitor additionally reduced the activity for exogenous FAs uptake, thus, leading to significant reduction of cell proliferation in anti-HER2 resistant breast cancer with PTEN-loss." (PMID 39920872, 2025). "Moreover, statistical analysis of gene data from the TCGA database confirmed that the expression trend of CAV1 in breast cancer tissues was consistent with that of CD36, with CAV1 expression significantly lower in cancer tissues compared with normal tissues." (PMID 41267927, 2025). "We first assessed endogenous CD36 protein levels in different breast cancer cell lines." (PMID 41267927, 2025). "Furthermore, tamoxifen (a breast cancer drug) blocks PPARγ nuclear translocation and inhibits CD36 gene transcription, reducing foam cell formation." (PMID 40563926, 2025). "CD36 inhibition significantly reduces breast cancer metastasis." (PMID 40002245, 2025). "However, other well‐documented reports have indicated that epithelial, endothelial, or stromal CD36 expression is negatively correlated with breast cancer proliferation and invasiveness." (PMID 41267927, 2025). "However, in patients with HER2+ breast cancer, elevated CD36 expression correlates with a poor prognosis." (PMID 40565366, 2025). "The overexpressed CD36 might contribute to the transport of free FAs into breast cancer cells from surrounding adipocytes to support tumor growth and cancer progression." (PMID 39920872, 2025). "Moreover, CD36 plays a role in supporting metastasis by regulating lipid balance when breast cancer stromal detachment occurs." (PMID 38779664, 2024). "Feng and colleagues found that CD36 acted as a key player in resistance to lapatinib in human epidermal growth factor receptor 2 (HER2)-positive breast cancer cells, and inhibiting CD36 restored sensitivity to lapatinib and triggered apoptosis in those lapatinib-resistant cells." (PMID 39834807, 2024). "CD36, known as FA translocase, is also a crucial enzyme involved in the uptake of FAs, and evidence suggests that it contribute to breast cancer progression and up‐regulated in tumour cells and is responsible for the uptake of exogenous FAs into cell membranes." (PMID 38332687, 2024). "However, tumoral stroma and microvessels show downregulation in CD36 expression compared to the surrounding tissues 1, as demonstrated for breast cancer." (PMID 38370376, 2024). "In addition, analysis of data from the NeoALTTO trial showed that CD36 increased in HER2-positive breast cancer after treatment with lapatinib and trastuzumab in the neoadjuvant setting and it was correlated with poor prognosis." (PMID 39624081, 2024).
breast carcinoma (continued). "Furthermore, breast cancer cells unresponsive to the HER2 inhibitor lapatinib exhibited high CD36 expression, which in turn induced metabolic rewiring by increasing FA uptake." (PMID 39624081, 2024). "Another piece of evidence showed that CD36 could promote proliferation and migration in breast cancer cells, pointing out their pro-tumorigenic role in breast cancer." (PMID 38276607, 2024). "Therefore, CD36-mediated exogenous FA uptake by cancer cells can be regarded as a primary survival mechanism of HER2-positive breast cancer." (PMID 37174034, 2023). "Indeed, the mevalonate precursor enzyme HMGCS1 is a marker of CSC enrichment in breast cancer, whereas CD36, the receptor for the palmitic acid, is overexpressed in CD44-positive metastasis-initiating cells in oral squamous cell carcinoma." (PMID 36732018, 2023). "Importantly, work from our group has also demonstrated a role for CD36 in mediating the acquisition of resistance to HER2-targeted therapies in breast cancer." (PMID 37371076, 2023). "In addition, SLIT3 was identified as an active ligand secreted from CD36+ FBs that induced growth suppression of MDA-MB-231 breast cancer cells." (PMID 36752296, 2023). "Notably, we found that CD36 expression predicts a poor prognosis among patients with HER2+ breast cancer and that its expression also increases among patients following a treatment with HER2-targeted therapy." (PMID 37371076, 2023). "In breast cancer patients, CD36 expression increased significantly after anti-HER2 treatment." (PMID 35743814, 2022). "Thus, this points to the possibility of stratifying breast cancer patients based on CD36 expression to determine their suitability for tamoxifen-based chemotherapy." (PMID 35448537, 2022). "Here, we have extended our previous findings that FBs expressing CD36, a receptor initially discovered through its roles in lipid uptake and adipogenesis, secrete a cocktail of protein ligands that inhibit the growth of certain types of breast cancer." (PMID 36361532, 2022). "Moreover, CD36-mediated metabolic rewiring of breast cancer cells has been shown to promote resistance to therapy." (PMID 36344546, 2022). "Many tumor cells express CD36, including certain types of breast cancer, some melanomas, renal carcinomas, and gliomas, and in these settings CD36 may be enriched in tumor initiating cells, or so-called cancer stem cells." (PMID 35438721, 2022). "This suggests that CD36 can be used as a specific target for fatty acid metabolism of macrophages in lung cancer and breast cancer to improve the tumor microenvironment while reducing the influence of M2-type macrophages in other normal tissues, thus reducing the damage to the autoimmune system." (PMID 36387147, 2022). "In HER2+ breast cancer patients, high CD36 expression correlates with poor prognosis." (PMID 36568966, 2022). "Thus CD36 can be used as a biomarker for diagnosis and can also be used as a target for treatment of breast cancer." (PMID 35888767, 2022). "Oestradiol downregulated CD36 in several breast cancer cell lines and promoted their proliferation." (PMID 35448537, 2022). "Indeed, an inverse relationship has also been found between CD36 expression levels and aggressiveness: more aggressive breast cancer cell lines such as MDA-MB-231 have lower CD36 expression levels than that of less aggressive ones, such as MCF-7." (PMID 35448537, 2022). "Furthermore, xenografts from lapatinib-resistant breast cancer cells treated with an anti-CD36 antibody were sensitized to lapatinib, demonstrating a key role of CD36 in the development and therapy response of HER2+ breast tumors." (PMID 36568966, 2022). "This study suggested a negative regulatory role of CD36 in CAFs, and this negative regulatory role may be manifested mainly in breast cancers, especially those with a high mammography density." (PMID 36354702, 2022). "CD36 increases proliferation and migration of ER+ breast cancer cells." (PMID 36114448, 2022).
breast carcinoma (continued). "Indeed, blocking the uptake of FA by inhibition of fatty acid receptor CD36 has been shown to impair metastasis in human breast cancer-derived tumours." (PMID 36329893, 2022). "Furthermore, CD36 expression promotes radio and chemoresistance in breast cancer, AML, MCL, and CRC, which are known to be (at least partially) mediated by CSCs." (PMID 36568966, 2022). "In addition, CD36 is closely related to the survival and metastasis of numerous tumors, such as lung cancer, bladder cancer, breast cancer, and melanoma." (PMID 35896782, 2022). "SIRT1 has been demonstrated to modulate several intracellular signaling protein molecules, including protein kinase B (PKB), B-cell lymphoma 2 (Bcl-2), metadherin (MTDH), Frizzled 7, EMT-related proteins, and the cluster of differentiation 36 (CD36), in breast cancer cells." (PMID 36291902, 2022). "However, the molecular mechanisms and regulators of CD36 activity in breast cancer cells remain largely unexplored." (PMID 34561446, 2021). "Taking all together these findings indicate that inhibiting both CD36 and FABP4 induces significant accumulation of unmetabolized lipid, resulting in apoptosis in breast cancer cells and chemical inhibitors of CD36 and FABP4 effectively reduces tumour growth in vivo." (PMID 34561446, 2021). "Neutralising antibodies that block CD36 completely inhibited the formation of metastasis in orthotopic mouse models of human oral cancer, and CD36 inhibition impaired metastasis in human melanoma and breast cancer-derived tumours." (PMID 33845831, 2021). "More specifically, retrospective analyses suggest that elevated levels of CD36 correlate with poor prognosis in patients with glioma, cervical cancer, ovarian cancer, lung cancer, squamous-cell carcinoma, bladder cancer, and luminal A breast cancer." (PMID 34215227, 2021). "Indeed, CD36 inhibition impaired angiogenesis as well as migration and invasion of breast cancer cell lines." (PMID 33808259, 2021). "An exception was MCF7, a human breast cancer cell line found to express glycosylated CD36." (PMID 34314388, 2021). "Moreover, patients expressing this basal B-specific splicing signature also expressed newly identified biomarkers of metastasis-initiating cells, like CD36, supporting a more invasive phenotype for this basal B-like breast cancer subtype." (PMID 33845831, 2021). "In conclusion, CD36 is a key player in adipocyte-breast cancer cell interaction." (PMID 34561446, 2021). "To identify signalling pathways activated, following co-culturing, and potentially involved in CD36-dependent induction of EMT and stemness, we determined the levels of various oncogenic pathway proteins in adipocyte co-cultured breast cancer cells, with abrogated CD36 activity, by western blotting." (PMID 34561446, 2021). "CD36 inhibition induces de novo lipogenesis in breast cancer cells." (PMID 34561446, 2021). "We also examined the effect of CD36 on breast cancer cell motility." (PMID 34561446, 2021). "Importantly, inhibition of CD36 reduced lipid droplet accumulation and attenuated the migration and invasion of the breast cancer cells." (PMID 31847105, 2019). "We also discovered an unknown miR-375 transfer mechanism from apoptotic breast cancer cells to TAMs involving CD36, which might pave the way for identifying new drug targets in breast cancer." (PMID 30850595, 2019). "Activation of CD36 expression may enhance progression and metastasis of several types of cancers including breast cancer." (PMID 30573731, 2018). "Therefore, our study unveils a pro-tumorigenic role of CD36 in breast cancer by enhancing proliferation/migration of breast cancer cells while attenuating tamoxifen-inhibited ER-positive cell growth." (PMID 30573731, 2018).